ARC (activity regulated cytoskeleton associated protein)
Diseases named in the same sentence as ARC in open-access papers (continued):
Sharing a sentence is not in itself a finding about the gene and the disease.
Alzheimer disease (5 papers, 2019 to 2022). A progressive, neurodegenerative disease characterized by loss of function and death of nerve cells in several areas of the brain leading to loss of cognitive function such as memory and language. "ARC has been previously implicated in Alzheimer’s disease as an enhancer of A-beta production, with increased ARC protein in the medial frontal cortex of Alzheimer’s patients." (PMID 31372185, 2019). "The postsynaptic network was found to be enriched in proteins associated with ARC-related synaptic plasticity, ASD, and late-onset Alzheimer’s disease." (PMID 35914814, 2022). "Previous studies have shown that abnormal expression of ARC in the brains of patients with Alzheimer’s Disease (AD) leads to the disturbance of synaptic plasticity." (PMID 35547627, 2022). "The same interactome was also found to be enriched in proteins involved in ARC-related synaptic plasticity, ASD, and late-onset Alzheimer’s disease (LOAD)." (PMID 35914814, 2022).
depression (5 papers, 2015 to 2025). "In most of the top models, a consistent dysregulation of MAP kinase pathway was identified and the genes NR4A1, BDNF, ARC, EGR2, and PDE7B were consistently downregulated as in humans with depression." (PMID 34997033, 2022). "Notable downregulated genes matching depression were: BDNF, the glucocorticoid receptor, NR3C1, and activity related genes, EGR1, FOS, NR4A1, FOSB, and ARC." (PMID 34997033, 2022). "Except for ARC, GRIK2 and GRID2, belonging to inotropic glutamatergic receptors, were shown to participate in neurodegeneration and psychiatric diseases, such as autism, Huntington disease and major depression." (PMID 33969375, 2021).
gastric cancer (5 papers, 2015 to 2021). A primary or metastatic malignant neoplasm involving the stomach. "miR-185 was reported to increase gastric cancer sensitivity to cisplatin and doxorubicin by inhibiting the expression of ARC." (PMID 27016414, 2016). "Significantly expressed phosphorylated ARC was also observed in gastric cancer tissues compared with normal gastric tissues." (PMID 26172393, 2015). "However, in other cancer cell lines such as human melanoma cell line ARC is predominantly distributed in cytoplasm and our previous study found that ARC was localized in cytoplasm in human gastric cancer SGC-7901 cells and human cervical carcinoma HeLa cells." (PMID 26172393, 2015).
neuroblastoma (4 papers, 2013 to 2021). Neuroblastoma (NB) is the most common solid, extracranial childhood tumor. "Brazilian green propolis has been shown to protect SH-SY5Y neuroblastoma cells from neurodegenerative damage by upregulating brain-derived neurotrophic factor (BDNF) and activity-regulated cytoskeleton-associated protein (ARC), proteins involved in memory." (PMID 34444688, 2021). "It was also shown to modulate Ca2+ entry through ARC channels in the SH-SY5Y neuroblastoma cell line." (PMID 33424550, 2020). "Using human neuroblastoma cells as a model, they attributed the effects to anti-oxidative properties of propolis, expression of brain-derived neurotrophic factor (BDNF), and activity-regulated cytoskeleton-associated protein (Arc), as being the critical factors of synapse efficacy." (PMID 35011307, 2021). "The overexpression of SARAF in neuroblastoma cells attenuated the arachidonic acid (AA)-induced Ca2+ response, and the transfection of SARAF siRNA enhanced AA-stimulated Ca2+ influx via ARC channels." (PMID 33424550, 2020). "In flow-cytometry analysis, down-regulation of postsynaptic density and dendrite spine morphology regulatory proteins (ARC, NMDAR1 and GRM1) was confirmed in both clade B and C infected primary human astrocytes and SK-N-MC neuroblastoma cells." (PMID 23620748, 2013). "Similarly, we have also observed significantly decreased expression of ARC, NMDAR1 and GRM1 proteins in clade B and C infected SK-N-MC neuroblastoma cells than the control cells (data not shown)." (PMID 23620748, 2013).
prostate carcinoma (4 papers, 2021 to 2022). A carcinoma that arises from epithelial cells of the prostate gland. "Interestingly, in breast and lung cancer cells, Orai3 was demonstrated to encode a homomeric SOCE channel whereas in prostate cancer cells Orai3 was shown to constitute a heteromeric ARC channel." (PMID 34885048, 2021). "A prognostic model composed of seven protein-coding genes (FOXN4, MGAM, MMP26, ARC, SOX11, PRAME, and VWA5B2) was established, and it was strongly associated with biochemical recurrence following radical prostatectomy in prostate cancer." (PMID 37255653, 2022). "Nevertheless, in both studies, the formation of Orai1-Orai3 heterooligomeric ARC channels has been found to play a role in prostate cancer cell development." (PMID 34360783, 2021). "The ARC channels were recently shown to mediate prostate cancer and PC progression." (PMID 34885048, 2021). "Moreover, overexpression of Orai3 enhanced the number of ARC channels together with proliferation, while apoptosis of prostate cancer cells was decreased." (PMID 34360783, 2021). "While ARC activation is dependent on STIM1 in HEK293 cells, in prostate cancer cells, silencing of the STIM1 expression did not alter the ARC activation, suggesting a STIM1-independent mechanism." (PMID 35682546, 2022).
breast carcinoma (3 papers, 2007 to 2024). "The apoptotic genes SPP1 and SFRP1 are candidate tumor suppressors for various cancers; AXL gene is a proto-oncogene, and NOL3 (ARC, apoptosis repressor with CARD domain) is induced in human breast cancer and confers chemo- and radiation-resistance." (PMID 19455236, 2007).
Cognitive impairment (3 papers, 2015 to 2020). Abnormal cognition is characterized by deficits in thinking, reasoning, or remembering. "Given ARC's key role in synaptic plasticity, we hypothesized that genetic variations in ARC may contribute to interindividual variability in human cognitive abilities or to attention‐deficit hyperactivity disorder (ADHD) susceptibility, where cognitive impairment often accompanies the disorder." (PMID 26516611, 2015).
alcohol dependence (2 papers, 2019 to 2021). Physical and psychological dependence on alcohol. "Deficits of BDNF signaling in the amygdala decreased the levels of the activity-regulated cytoskeleton-associated protein (ARC) and reduced synaptic plasticity while increasing the risk of alcohol dependence in adulthood." (PMID 34203457, 2021).
amblyopia (2 papers, 2023 to 2025). Decreased vision that results from abnormal visual development. "The expression of ARC/Arg3.1 is associated with monocular form deprivation amblyopia and apoptosis of lateral geniculate body cells." (PMID 36597053, 2023). "Therefore, we examined changes in ARC/Arg3.1 in the lateral geniculate body in amblyopia to investigate the significance of this body in the pathogenesis of amblyopia and provide theoretical support for the occurrence and development of amblyopia." (PMID 36597053, 2023). "Recent studies demonstrated that MD increases neuronal dysfunction in LGN, accompanied by a significant reduction of ARC/Arg3.1 expression, whose changes from visual deprivation-driving may contribute to synaptic impairment and subsequent amblyopia development." (PMID 40655949, 2025). "The change of neuron number in the lateral geniculate body further leads to the decrease of ARC/Arg3.1 expression, which leads to abnormal activities such as LTP and LTD, and finally promotes the further development of amblyopia." (PMID 36597053, 2023). "On the other hand, we only compared the expression of ARC/Arg3.1 in the lateral geniculate body of amblyopia kittens and normal kittens and did not study the change of its expression in different layers of the lateral geniculate body." (PMID 36597053, 2023). "However, there has been no study on the correlation between the expression of ARC/Arg3.1 and amblyopia." (PMID 36597053, 2023).
amyloid (2 papers, 2021 to 2022). "For example, ARC protein expression decreases in the dentate gyrus and CA1 region of AD mice, and the neurons with amyloid plaque-associated dystrophic neurites fail to express ARC mRNA." (PMID 35547627, 2022). "It has been revealed that the ARC expression reduces in the dentate gyrus and CA1 region of AD mice, and the neurons with amyloid plaque-associated dystrophic neurites fail to express ARC mRNA." (PMID 34106879, 2021).
diabetic cardiomyopathy (2 papers, 2014 to 2015). Diabetic cardiomyopathy is a disorder of the heart muscle in people with diabetes. "Indeed, ARC silencing by siRNA resulted in cardiomyocyte pyroptosis, suggesting that ARC functions to suppress pyroptosis in diabetic cardiomyopathy." (PMID 25341033, 2014). "However, it is undeniable that the effect of mir-30d on diabetic cardiomyopathy may be mediated by a variety of mechanisms in addition to the foxo3a–ARC–caspase-1 pathway, and further investigation is required to unveil the other mechanisms involved." (PMID 25341033, 2014).
epilepsy (2 papers, 2012 to 2023). A brain disorder characterized by episodes of abnormally increased neuronal discharge resulting in transient episodes of sensory or motor neurological dysfunction, or psychic dysfunction. "ARC and Homer 1A have repeatedly been highlighted in the literature as proteins synthesized in response to neuronal activity (in epilepsy or in response to L-LTP-inducing stimuli)." (PMID 22792408, 2012).
mastitis (2 papers, 2024 to 2025). Inflammation of breast tissue during lactation or postpartum due to an obstructed duct or infection. "Among them, cnvr_137 contains genes such as LY6D, LYNX1, LYPD2, SLURP1,THEM6, PSCA, TSNARE1, and ARC associated to clinical mastitis in US Holstein dairy cows." (PMID 38771855, 2024).
myocardial infarction (2 papers, 2019 to 2022). Gross necrosis of the myocardium, as a result of interruption of the blood supply to the area, as in coronary thrombosis. "The results of downregulated miR-325-3p were controversial, previous results indicate that the overexpression of miR-325 in cardiomyocytes greatly enlarged the sizes of myocardial infarctions through the suppression of apoptosis repressor with caspase recruit domain (ARC)." (PMID 31248365, 2019).
adenoma (1 paper, 2021). A neoplasm arising from the epithelium. "Our results demonstrated that both cytoplasmic and nuclear ARC are overexpressed in FAP adenomas, thus in a homogenous collective." (PMID 33579312, 2021). "The expression of nuclear and cytoplasmic ARC in 212 adenomas from 80 patients was analyzed by immunohistochemistry." (PMID 33579312, 2021). "Strong cytoplasmic ARC expression was detected in 32.5% (n = 69/212), and moderate cytoplasmic staining (score 2) in 49.1% (n = 104/212) of adenomas." (PMID 33579312, 2021). "The results of our study demonstrated both cytoplasmic and nuclear ARC overexpression in FAP adenomas." (PMID 33579312, 2021). "Nuclear expression of ARC in over 75% of cells was present in 30.7% (n = 65/212) of investigated adenomas, and nuclear expression in 10–75% of cells was detected in 62.7% (n = 133/212)." (PMID 33579312, 2021). "We suggest that ARC might have a regulatory role in the development of FAP adenomas, and that nuclear ARC in particular might have a greater effect on carcinogenesis than previously thought." (PMID 33579312, 2021). "The highly significant correlation between nuclear ARC and nuclear β-catenin suggested that ARC might be regulated by β-catenin in FAP adenomas." (PMID 33579312, 2021). "In this study, cytoplasmic overexpression of ARC was found in approximately 82% of FAP adenomas." (PMID 33579312, 2021). "ARC expression in under 10% of nuclei was found in 6.6% (n = 14/212) of adenomas." (PMID 33579312, 2021). "However, in FAP adenomas the Wnt/β-Catenin mediated regulation of ARC expression might be of particular relevance, as β-Catenin is accumulated due to its APC-mutation reasoned missing degradation." (PMID 33579312, 2021). "Moreover, the highly significant correlation (p = 0.001) between nuclear β-Catenin and nuclear ARC suggested that ARC might be regulated by β-Catenin not only in AML-cells but also in FAP adenomas." (PMID 33579312, 2021). "Of 217 FAP adenomas from 80 patients stained for ARC, 212 could be evaluated." (PMID 33579312, 2021). "Here, we show for the first time that ARC is overexpressed in the nucleus and cytoplasm of FAP adenoma cells, and that the correlation between its expression in both locations is highly significant." (PMID 33579312, 2021). "The highly significant correlation between nuclear ARC and nuclear β-Catenin also suggested that ARC might be transcriptionally regulated by β-Catenin in FAP adenomas." (PMID 33579312, 2021). "In addition to cytoplasmic overexpression, nuclear ARC was slightly overexpressed in 62.7% and strongly overexpressed in 30.7% of FAP adenomas investigated in this study." (PMID 33579312, 2021). "ARC was overexpressed in the nuclei and cytoplasm of most FAP adenomas investigated." (PMID 33579312, 2021).
cannabis dependence (1 paper, 2023). Physical and psychological dependence on the drug cannabis. "Specifically, the e-cigarette solvent vapor propylene glycol (PG) downregulated EGR2 and ARC mRNA expression in frontal cortex, an effect which was reversed by nicotine (NIC) and THC, suggesting that PG could have a protective role against NIC and cannabis dependence." (PMID 38002516, 2023).
cardiac ischemia (1 paper, 2002). "Alterations of pro-survival proteins such as the inhibitor of apoptosis protein on chromosome X (xIAP) and the apoptotic repressor protein (ARC) have not been evaluated in a murine model of cardiac ischemia." (PMID 12805954, 2002).
cognitive decline (1 paper, 2022). "A mounting body of evidence suggests that prenatal inflammation may enhance the rate of age-associated cognitive decline and may involve aberrant amounts of synaptic proteins in the hippocampus, including synaptotagmin-1 (Syt1) and activity-regulated cytoskeleton-associated protein (Arc)." (PMID 35574247, 2022).
colon adenocarcinoma (1 paper, 2015). "Another study shows interesting results that ARC locates only to cytoplasm in differentiated or poorly differentiated colon adenocarcinoma, meanwhile ARC locates to both cytoplasm and nucleus in moderately differentiated colon adenocarcinoma." (PMID 26172393, 2015).
dementia (1 paper, 2020). Loss of intellectual abilities interfering with an individual's social and occupational functions. "Likewise, Venn analysis of downregulated genes identified 3 genes, dual specificity phosphatase 6 (DUSP6), VGF nerve growth factor inducible (VGF), and activity regulated cytoskeleton associated protein (ARC) shared between dementia types." (PMID 32192109, 2020).
Dyskinesia (1 paper, 2013). A movement disorder which consists of effects including diminished voluntary movements and the presence of involuntary movements. "Finally, post-mortem analysis indicated that this reduction in dyskinesias was associated with changes in cFOS, FosB and ARC mRNA expression levels in the putamen." (PMID 23300984, 2013). "ARC appears as a key molecular player in the reduction of dyskinesia in both rodent and primate models of PD." (PMID 23300984, 2013).
endometrial cancer (1 paper, 2021). Primary or metastatic malignant neoplasm involving the endometrium (mucous membrane that lines the endometrial cavity). "Indeed, ChIP‐seq signal for the EGR1 protein in cultured cell lines (ECC1: endometrial cancer; K562: erythromyeloblastoid leukemia) overlapped that of the LDB2 protein in neurosphere cells at the promoter region of ARC." (PMID 33656268, 2021).
fragile X syndrome (1 paper, 2021). A genetic syndrome caused by mutations in the FMR1 gene which is responsible for the expression of the fragile X mental retardation 1 protein. "In Fragile X syndrome (FXS), ARC expression is enhanced by a reduction of the FMRP protein, a repressor of translation." (PMID 33656268, 2021).
idiopathic generalized epilepsy (1 paper, 2023). A generalised epilepsy that encompasses several common seizure phenotypes including childhood absence epilepsy, juvenile absence epilepsy, juvenile myoclonic epilepsy and epilepsy with generalized tonic-clonic seizures alone. "Authors suggest the presence of an idiopathic generalized epilepsy susceptibility allele in the ARC gene." (PMID 37483450, 2023).
Intellectual disability (1 paper, 2022). "FXS and AS are similar in that both syndromes show atypical DNA methylation that results in increased levels of Activity-Regulated Cytoskeleton-associated protein (Arc), causing reduced synaptic plasticity and disruptions in cerebral development which often lead to intellectual disability." (PMID 35651825, 2022).